GSK3B (glycogen synthase kinase 3 beta)
Diseases named in the same sentence as GSK3B in open-access papers (continued):
Sharing a sentence is not in itself a finding about the gene and the disease.
tumor (continued). "Progression-free and overall survival rates were compared between patients with low or high expression of active GSK3β in the primary tumor." (PMID 28423558, 2017). "Immunoprecipitation of tumor lysates showed that GTGKT peptide inhibited the binding of CAGE to GSK3β." (PMID 28099142, 2017). "It has been investigated that the inhibition of GSK3B induces cell death including mitotic devastation by dysregulation of centrosome in tumor cells." (PMID 28587194, 2017). "Once activated, PI3K/AKT induces the phosphorylation of GSK-3β and subsequently regulates the expression of β-catenin which plays an important role in various tumor growth, migration and invasion." (PMID 28410212, 2017). "A series of studies have found that both Cox-2/PGE2 and PI3K/AKT/GSK3β/β-catenin signaling pathway can lead to tumor progression." (PMID 29358963, 2017). "Mechanism study found that ALX4 exerted its anti-tumor function by suppressing the Wnt/β-catenin pathway through promoting the phosphorylation degradation of β-catenin in a GSK3β dependent manner." (PMID 29183346, 2017). "Overexpression of ZNRF3 inhibited cell growth and rescued the tumor-promoting role of miR-146a via inhibition of GSK-3β/β-catenin signaling pathway." (PMID 29088784, 2017). "Inhibition of GSK-3β attenuates cell survival and proliferation, induces cell senescence and apoptosis, and sensitizes tumor cells to chemotherapeutic agents and ionizing radiation." (PMID 28427240, 2017). "The obtained results show a significant reduction in the GSK3β protein in shKLRC3 compared to the control cell line and the primary culture derived from a patient's tumour." (PMID 27641066, 2017). "Glycogen Synthase Kinase-3β (GSK3β), a serine/threonine protein kinase, has been considered as a potential tumor suppressor due to its ability to phosphorylate other proteins; it also has numerous cellular targets including cyclin D1 and β-catenin." (PMID 29216929, 2017). "Tideglusib displayed pharmacokinetic potency in reducing GSK3β-mediated phosphorylation of phospho-β-catenin and consequent increase in total β-catenin in vitro for primary tumor cultures with demonstrated over-expression of GSK3α and GSK3β." (PMID 28968964, 2017). "It is also known that Akt activation phosphorylated GSK3β at Ser9 and inhibited GSK-3β activity, leading to nuclear β-catenin accumulation and ultimately triggering tumor progression." (PMID 29254202, 2017). "We further consolidated our observation by detecting the expression of ALX4, β-catenin, p-β-catenin and GSK-3β in xenograft tumor tissues by WB." (PMID 29183346, 2017). "This suggests aberrant GSK3β activity in the tumor cells as a new prognostic factor in GBM and clinically rationalizes the strategy of targeting of this kinase for treatment of GBM." (PMID 28423558, 2017). "Analogously, we found significant inhibition of AKT (P < 0.05) and GSK3B (P < 0.01) phosphorylation in tumour xenografts of A2M* treated mice." (PMID 29281661, 2017). "GSK3β is constitutively active in unstimulated cells and acts as a “tumor suppressor” since maintains in inactivate state different molecules related to cell growth, such as cyclin D1 or c-Myc." (PMID 27634891, 2016). "It was reported that GSK-3β exhibited both oncogenic and tumor-suppressive roles in the context of different cancer types." (PMID 27846906, 2016). "p65 nuclear translocation reportedly induces CSN2 upregulation followed by phosphorylation of GSK3β at serine 9, which promotes tumor metastasis and EMT." (PMID 26942699, 2016). "In the cancer field, GSK-3β is commonly recognized as a putative tumor suppressor due to its well-established function as a repressor of β-catenin signaling and phosphorylation-dependent down-regulation of cell-cycle regulators cyclin D1, cdc25, and c-Myc." (PMID 27602497, 2016).
tumor (continued). "In summary, we have demonstrated that Bufalin can induce cellular apoptosis and cell cycle arrest, reduce cell metastasis, and inhibit xenograft tumor growth mainly through repression of the integrin α2β5/FAK/ATK/GSK3β signal pathway." (PMID 26758421, 2016). "Various upstream proteins, such as ERK, mTOR and Wnt, are involved in the inactivation of GSK3β and tumor metastasis." (PMID 27806330, 2016). "GSK-3β also functions as a tumor suppressor, because GSK3β can suppress the Wnt/β-catenin pathway by phosphorylating β-catenin." (PMID 28036353, 2016). "Immunohistochemical analysis demonstrated that GSK-3β expression was significantly downregulated in the HSA-129 group compared with the control group in nude mice tumor tissues." (PMID 27050373, 2016). "Administration of the GSK-3β inhibitors significantly reduced the tumor volume in mice as early as 2 weeks after treatment was initiated." (PMID 27780915, 2016). "GSK3β is known to be involved in tumor development, but its role in tumorigenesis remains controversial." (PMID 27494834, 2016). "Results from previous studies have suggested that the overexpression of AURKA increases the level of p-GSK-3β, p-Akt1 and β-catenin and plays an important role in cell proliferation, tumor progression and metastasis." (PMID 27121204, 2016). "In cancer, GSK-3β has been reported as a “tumor suppressor” by repressing neoplastic transformation and tumor development." (PMID 27123999, 2016). "Among the components of the positive feedback loop, GSK3β has been intensively studied for its role as either a tumor suppressor or promoter depending on the type of tumor." (PMID 26655089, 2016). "It's important to note that GSK3β plays a dual role in GBM either as a tumor suppressor and tumor promoter." (PMID 27792996, 2016). "We also examined the significance of the functional relationship between MAPK1/2 and GSK3β phosphorylation in primary human tumor samples." (PMID 28725457, 2015). "All of these independent observations demonstrate a higher expression level of GSK3β than GSK3α in oral tumor tissue samples." (PMID 25645517, 2015). "We found that TKO HCC tumour zones are depleted of glycogen in contrast to neighbouring non-tumour zones, thereby correlating with increased Gsk3b and Pygb expression." (PMID 26639898, 2015). "In contrast to un-irradiated controls, we found a dose-dependent increase in phosphorylation of GSK-3β in all three of the tumor lines examined." (PMID 26280348, 2015). "We thus detected the EMT marker in Rab3D knockdown or overexpression tumor cells, and accordingly our data showed that Rab3D regulates EMT induction of tumor cells via the activation of Akt/GSK-3β/Snail pathway." (PMID 25823663, 2015). "As expected, Z86 treatment reduced the phosphorylation of GSK3β (Ser9) and increased the levels of phospho-β-catenin (Ser33/Ser37/Thr41) in the tumor tissues compared with the vehicle-treated group." (PMID 27551464, 2015). "The role of GSK-3β in radiation cytotoxic response in tumor cells is complex due to its multifunctional regulation of other key cellular pathways including cell proliferation, survival, cell cycle and cell differentiation." (PMID 26280348, 2015). "In fact, under proteasome stress tumor cells early activated autophagy, chronically inhibited GSK-3β and recovered cell proliferation, whereas MCF10A cells did not." (PMID 25941117, 2015). "The functional analysis reveals that ectopic expression of GSK-3β suppressed angiogenesis and tumor growth in vivo." (PMID 26388612, 2015). "Here, we demonstrated that normal mammary cells behaved like tumor cells when GSK-3β was pharmacologically inhibited." (PMID 25941117, 2015). "We showed that ASX inhibited the invasion of tumor cells via NF-κB p65 and Wnt/β-catenin by reducing the phosphorylation of GSK-3β (Ser9) in liver oncogenesis." (PMID 26404320, 2015).
tumor (continued). "While GSK3β promoted cancer development and growth in some types of cancer, it had a tumor suppressor function in other types since a decrease in GSK3β function or expression was observed in these tumors." (PMID 25741280, 2015). "Accordingly, we incubated tumor cells with a GSK3β inhibitor, BIO, prior to treating with amiodarone and analysis of Snail and Twist." (PMID 26515726, 2015). "There have been a number of conflicting reports concerning the extent of tumor progression and the expression of total GSK3β in human cancers." (PMID 25645517, 2015). "This once again support our findings that GSK3α-mediated cell survival and proliferation promotes tumor growth in both early and advanced stages, and that GSK3β/β-catenin-mediated EMT promotes cell motility, invasion and micrometastasis in the advanced stages." (PMID 25714023, 2015). "Next, we checked the protein levels and phosphorylation status of β-catenin and GSK3β in tumor tissues." (PMID 27551464, 2015). "To determine how inhibition of PAX3-FOXO1 phosphorylation affects ARMS tumor cell migratory ability, we performed wound-healing assays in the presence of GSK3β inhibitors or with cells stably expressing PAX3-FOXO1 phosphomutants." (PMID 25821947, 2015). "As observed with total GSK-3β, radiation caused an up-regulation in the expression of total AMPK in all three tumor cell lines." (PMID 26280348, 2015). "GSK-3β is an important molecule to regulate Wnt/beta-catenin signaling, and is a key regulator of tumor development." (PMID 26388612, 2015). "The increase in GSK3β expression we observed in Group 1 tumours was frequently accompanied by an equivalent increased phosphorylation of the inhibitory S21/9 sites." (PMID 25486534, 2014). "It appears, therefore, that the drastic anti-tumor effects of GSK-3β inhibition cannot be solely explained by modulation of the androgen-receptor axis." (PMID 25344861, 2014). "In addtion, our IHC results showed that GSK3β is localized predominantly in the cytoplasm in patient and xenograft tumor tissues." (PMID 24618715, 2014). "Together, these findings identify GSK3β as a tumor promoter and a potential therapeutic target for NSCLC." (PMID 24618715, 2014). "In NSCLC GSK3β has been recently reported to be over-expressed in tumour tissue compared to normal tissue isolated from the resection margin and this was found to correlate with poor patient prognosis." (PMID 25486534, 2014). "In this study, the intrinsic inhibition of GSK3β arrested NSCLC tumor cells in the G0/G1 phase in vitro." (PMID 24618715, 2014). "Based on these functions, GSK3β is a potential tumor suppressor, and the inactivation of GSK3β has been reported in many cancer cells." (PMID 24618715, 2014). "NVP-BEZ235 is a dual inhibitor of both PI3K and mTOR and promotes the degradation of MYCN to effectively reduce tumor burden in the MYCN transgenic mouse via GSK3β activation." (PMID 24391509, 2014). "Certain changes of expression of AKT/GSK3β/β-catenin/E-cadherin signaling pathway-related proteins were in tumor tissues, which were related to the bufalin dose." (PMID 24581171, 2014). "With regard to relationship between PI3K/AKT and vIL-6, we found that PI3K/AKT activated while PTEN/GSK-3β was inactivated in both vIL-6-producing 4E3 cells and 4E3-mediated tumor tissues from CAM and nude mice models." (PMID 23301033, 2013). "In mammals, DIFs affect the activity of protein kinases such as ERK and GSK-3β in some tumor cells and arrest the cell cycle at the G0/1 phase by inhibiting the expression of cyclin D and the phosphorylation of retinoblastoma protein." (PMID 23977224, 2013).
tumor (continued). "Future studies should examine the potential of such therapeutics to deplete the CloP and their affect on overall tumor progression and should also address the importance of Notch, GSK3-β, FoxoM1, and miR-371-373 that can regulate β-catenin activity." (PMID 23468473, 2013). "In summary, TQ interferes with polyp progression in ApcMin mice through induction of tumor-cell specific apoptosis and by modulating Wnt signaling through activation of GSK-3β." (PMID 23668310, 2013). "Immunoblot analysis of tumor samples showed increased levels of β-catenin accompanied by decreased phospho-β-catenin and increased phospho-GSK3β after 56Fe radiation compared to control and γ radiation groups." (PMID 23555653, 2013). "Taken together, we found that overexpression of βKlotho suppressed tumor formation by regulating Akt/GSK-3β/cyclin D1 signaling pathway." (PMID 23383245, 2013). "The GSK-3β activator, sodium nitroprusside dehydrate (SNP), augmented the anti-tumor effects of hUC-MSCs and decreased the expression of β-catenin." (PMID 23646150, 2013). "In summary, TQ interferes with polyp progression in APCMin mice by inducing tumor cell-specific apoptosis and by modulating Wnt signaling through GSK-3β activation, β-catenin translocation and reduction of nuclear c-myc." (PMID 23668310, 2013). "Clarification of the role of GSK3β in modulating the anti-tumor effects of radiation is therefore a priority for future investigations." (PMID 23408967, 2013). "EGF can inactivate GSK3β, leading to the degradation of c-Myc and β-catenin, which are overexpressed in tumour cells." (PMID 22343623, 2012). "We recently reported that tumor cell-derived factor(s) activated macrophages to produce IL1β, which in turn inactivated GSK3β, increased the levels of unphosphorylated β-catenin and stimulated Wnt signaling in HCT116 cells." (PMID 23029025, 2012). "With regard to the inhibition of tumour growth, the addition of U50, 488H to H1975 cells produced a concentration-dependent decrease in phosphorylated-glycogen synthase kinase 3β (p-GSK3β)." (PMID 22343623, 2012). "Analysing these residual tumour cells we identified a gene expression pattern encompassing GSK3B, CTNNB1 and NOTCH2, which strongly predicts prognosis of the patients." (PMID 22970250, 2012). "We propose that the GSK3β, β-catenin and MnSOD axis represents a potential target to lower the resistance to oxidative stress of tumor harboring oncogenic EGFR and PI3KCA." (PMID 22662165, 2012). "Macrophages and IL1β inactivate GSK3β in both HCT116 and Hke-3 cells and, consistently, stabilize Snail independently of the presence kRas mutations in tumor cells." (PMID 23029025, 2012). "Of special interest is the involvement of GSK-3β in cancer with data supporting a role as a tumor suppressor and tumor promoter, a discrepancy that at least in part depends on both cell type and signaling environment." (PMID 22675363, 2012). "GSK3β was also phosphorylated in these tumors, as well as in non-tumor mammary gland tissue from the Pik3caH1047R mutant mice." (PMID 22666336, 2012). "The gene expression profiling of the 63 tumours of patients with TRG2 showed, that high expression levels of GSK3B, DNMT1 and CTNNB1 were significantly associated with better survival (conditional inference test: p = 0.006, 0.041, and 0.043, respectively)." (PMID 22970250, 2012). "While a recent study has described an attenuation of cell survival and proliferation upon GSK3β inhibition, our data rather support the notion of GSK3β acting as a tumor suppressor." (PMID 22111880, 2011). "We review recent studies that demonstrate the anti-tumor effects of GSK3β inhibition alone or in combination with chemotherapy and radiation." (PMID 24212624, 2011). "Here, we present evidence that the tumor-like growth of mouse embryonic stem cells (mESCs) is suppressed by short-term serum-free culture, which is reversed by pharmacological inhibition of Gsk3β." (PMID 21731714, 2011).
tumor (continued). "Based on its role in various pathways including ERK1/2 activation, β-catenin signalling and c-Myc/cyclin D1 expression, previous studies have suggested a putative role of GSK3β as a tumor suppressor." (PMID 22111880, 2011). "In this report, we present experimental evidence to suggest that short-term CDSF culture reduces the tumor-like growth of mESCs, which is reversed by pharmacological inhibition of Gsk3β." (PMID 21731714, 2011). "Because of the following two observations, we consider the effect of Bmp4 on Gsk3β or the tumor-like growth of mESCs antagonistic or indirect." (PMID 21731714, 2011). "Although the role of Gsk3β in the self-renewal of ESCs has been established, it is suggested with these data that Gsk3β governs the tumor-like growth of mESCs by means of a mechanism different from the one to support the pluripotency of ESCs." (PMID 21731714, 2011). "Activated glycogen synthase kinase-3ß serine-9 phosphorylation (GSK-3β, S9P) is also required for tumor cell survival and anti-apoptosis." (PMID 22096483, 2011). "In this regard, other groups have shown that survival of different tumor cells depends on GSK-3β activity trough a NF-κB-dependent pathway." (PMID 21079728, 2010). "As previously reported, DIF-1 suppressed the Wnt/β-catenin signaling pathway by activating GSK-3β in tumor cells." (PMID 20843378, 2010). "Over-expression of GSK-3β can induce apoptosis in tumor cells, whereas inactivation of GSK-3β through phosphorylation of the Serine 9 residue can reduce apoptosis and enhance cell survival." (PMID 21079779, 2010). "Recent developments suggest an active role of glycogen synthase kinase 3 beta (GSK3 β) in various human cancers either as a tumor suppressor or as a tumor promoter." (PMID 20537194, 2010). "Overall, this evidence suggests the possible active involvement of GSK3β-mediated signaling in this neoplastic disease." (PMID 20537194, 2010). "Tumor-promoting phorbol esters inhibit GSK3β via a classical MAPK cascade by activating p90RSK (MAPKAP-KI)." (PMID 20537194, 2010). "It is now clear that GSK-3β functions in diverse cellular processes including proliferation, differentiation, survival, neoplastic transformation and tumor development." (PMID 20178594, 2010). "Previously, we reported that DIFs inhibited the Wnt/β-catenin signaling pathway via glycogen synthase kinase-3β (GSK-3β) activation, leading to cell cycle arrest at G0/G1 phase through suppression of cyclin D1 expression in various human tumor cells." (PMID 20843378, 2010). "In Wnt signalling, Axin interacts with many components of the pathway, including the adenomatous polyposis coli (APC) tumor suppressor, the serine/threonine kinases casein kinase Iα (CKIα) and glycogen synthase kinase 3β (GSK3β), and β-catenin." (PMID 18644116, 2008). "The estimated molecular weights of the proteins expressed in these tumours were as expected: 92 kDa for β-catenin, 46–48 kDa for GSK3β and approximately 55–60 kDa for Lef-1." (PMID 14520463, 2003). "By this criterion APC, GSK3β, and axin are potent tumor suppressors, whereas β-catenin is an oncogene." (PMID 14551908, 2003). "Beta-catenin is phosphorylated by glycogen synthase kinase 3β (GSK3β), in connection with the tumour-suppressor gene product adenomatous polyposis coli (APC) and Axin." (PMID 14520463, 2003). "The findings of GSK-3β in tumor biology often present a complex and sometimes contradictory." (PMID 40656954, 2025). "AKT/GSK-3β is an important mechanism to control tumor invasion and metastasis." (PMID 39949372, 2025). "Furthermore, we demonstrated that IR-546 induces apoptosis and inhibits metastasis of tumor cells by suppressing the AKT/GSK3β signaling pathway in vitro and in vivo." (PMID 40495167, 2025).